RAB27A (RAB27A, member RAS oncogene family)
Diseases named in the same sentence as RAB27A in open-access papers (continued):
Sharing a sentence is not in itself a finding about the gene and the disease.
cancer (continued). "Furthermore, Rab27a-proficiency by cancer cells is important for their ability to colonize distant organs independent of pre-metastatic niche conditioning, potentially through alterations in EMT and/or mesenchymal-to-epithelial (MET) properties." (PMID 32355248, 2020). "Overall, these observations suggest that Rab27a may be important for suppressing some of the intrinsic abilities of cancer cells to invade tissue at early seeding stages." (PMID 32355248, 2020). "This suggests that addition of cancer-educated myeloid cells can partially compensate for deficient metastatic outgrowth in the absence of Rab27a expression in cancer cells." (PMID 32355248, 2020). "Rab27a/b or nSMase2 involved in the cancer cell metastasis via miRNA-mediated exosomal pathways." (PMID 32957534, 2020). "Additionally, Rab27A/B-induced exosome secretion decreases the expression of tumor-suppressive microRNAs, including miR-23b and miR-921, leading to cancer growth and metastasis." (PMID 31438991, 2019). "Evidence supporting the role of human Rab27a (hRab27a) in multiple cancer types suggests that the inhibition of this GTPase could be a target for cancer therapy." (PMID 30950405, 2019). "The role of Rab27A/B in exosome release has been confirmed in many additional cancer cell types." (PMID 30925917, 2019). "However, more studies are needed to confirm the roles of Rab27A/B in cancer because Rab27A and Rab27B have been reported to have cancer type-dependent functions; the roles of Rab27A/B in cancer remain elusive." (PMID 30081925, 2018). "Rab27A and Rab27B promote exosome secretion in various types of cancer." (PMID 30081925, 2018). "Also, chemotaxis of cancer cells has been shown to be promoted by exosome secretion, but to be diminished by knockdown of the exosome regulator Rab27a." (PMID 30150937, 2018). "In addition to regulating exosome secretion in cancer cells, Rab27A/B also regulate exosome secretion in stromal cells." (PMID 30081925, 2018). "Moreover, as overexpression of Rab27a protein is relevant in the redistribution of the cell cycle, daphnane diterpenes -rich TH- and gnidilatidin-induced downregulation of Rab27, therefore, lowers the cancer cells invasiveness and metastatic abilities." (PMID 30157785, 2018). "Because the biological role of Rab27A/B is crucial for maintaining proper cellular function, aberrant expression of Rab27A/B may lead to cancer development." (PMID 30081925, 2018). "Altered expression of Rab27A/B is commonly observed in cancer." (PMID 30081925, 2018). "We found that Rab27A was overexpressed in 39 of 87 (44.8%) cancer cases." (PMID 29088864, 2017). "Recently, several studies reported the diverse function of Rab27A in many kinds of human cancers." (PMID 26070933, 2015). "In my view, these discrepant findings indicate that Rab27A may have different molecular mechanisms in different human cancer under specific circumstances." (PMID 26070933, 2015). "Rab27a has been suggested as a possible therapeutic target in cancer cells." (PMID 24587032, 2014). "Rab GTPases that regulate exocytosis (e.g., Rab27A and Rab37) could also be crucial for cancer progression." (PMID 25382899, 2014). "Improved knowledge of the downstream mediators of the effects of Rab27a in cancer cells may allow for the dissection of the different Rab27a-induced phenotypes and, thus, the generation of specific targeted therapies." (PMID 24587032, 2014). "Importantly, they showed that administration of a sEV release inhibitor or implantation of cancer cells that release a limited amount of sEVs (mEERL Rab27a+/- and Rab27b-/- cells) attenuated the development of pain, thus providing convincing evidence for a significant role of cancer sEVs in pain." (PMID 39811726, 2024).
cancer (continued). "In this study, through next-generation sequencing and in vitro experiments, we demonstrated that several miRNAs, including miR-127-3p, may have been sorted into exosomes and secreted extracellularly by RAB27A overexpression to accelerate cancer cell metastasis." (PMID 38685086, 2024). "Furthermore, Rab27a knockdown can reduce the expression of genes related to exosomal biogenesis and secretion in cancer cells and promote the proliferation activity of aspirin on NK cells, while Rab27a overexpression can weaken the activity and promote the apoptosis of NK cells." (PMID 37392173, 2023). "Rab27a mutations have not been described, thus far, in the context of cancer." (PMID 37641131, 2023). "Furthermore, MAPK/ERK signaling pathway plays a vital role in CRC progression and may be involved in RAB27A-mediated cancer progression." (PMID 36371494, 2022). "Therefore, it remains controversial whether high Rab27a expression is suitable for predicting cancer prognosis." (PMID 35053535, 2022). "Therefore, it seems that either different populations of immune cells at targeted organ sites are regulated by Rab27a proficient cancer cells; or there might be distinct types of systemic cues that are regulated by Rab27a that confer organ specificity." (PMID 32355248, 2020). "Hence, the strategies to block the exosomal release of miRNAs by the knockdown of Rab27a/b or nSMase2 genes could inhibit cancer cell metastasis and tumor invasion." (PMID 32957534, 2020). "According to previous studies, Rab27a and Rab27b have structural similarities and are functionally similar in that they are involved in the transport and exocytosis of secretory vesicles in various cell types, including melanocytes, neutrophil, and cancer cells." (PMID 32784729, 2020). "However, whether the altered expression of Rab27A/B in cancer is due to aberrant microRNAs expression is still unclear." (PMID 30081925, 2018). "The multiple activities of exosome may explain the complicated function of Rab27A in human cancer." (PMID 26070933, 2015). "As such this has been shown in some cancers for e.g. ESCRT components, syntenin, heparanase, small GTPases (such as Rab27A and Rab27B), SNARE proteins (such as SNAP23)." (PMID 35898875, 2022). "In the cancer cachexia model, inhibiting LLC-EVs release by knocking down the expression of Rab27A and Rab27B can alleviate muscle wasting." (PMID 33510128, 2021). "We found that downregulation of Rab27a perturbed expression of genes related to cell motility and increased an EMT gene signature in the cancer cells." (PMID 32355248, 2020). "Other molecules, such as RAB27A/B, TSG101, and TSAP6, have also been shown to be involved in the secretion of EVs from cancer cells." (PMID 32932657, 2020). "It is notable that high levels of Rab27A were detected in both well differentiated normal colon epithelia cells and cancer stem cells, indicating that it is not a specific cancer stem cell marker, but may rather serve a complementary role in promoting the exocrine activity in cancer stem cells." (PMID 27556511, 2016). "Supporting the important role played by EVs, parental CAFs efficiently enhanced MCF7 cell migration, while these cancer cells were not affected by co‐culture with Rab27a KD CAFs." (PMID 40091448, 2025). "Rab27A expression is upregulated in MDA-MB-231 grown as mammospheres compared with those grown as adherent cells, and reducing Rab27A expression decreases mammosphere formation by lowering the proportion of cancer-initiating CD44+/CD24−/low cells." (PMID 38543182, 2024). "We blocked the secretion of exosomes by conditionally knocking out (KO) Rab27a in the healthy pancreas (Pdx1-Flp; Rab27aFrt/Frt) and in PDAC cancer cells using the fast progression PDAC model (PKT iRab27a, Ptf1a-Cre; LSL-KrasG12D/+; Tgfbr2loxP/loxP; R26LSL-FLPoERT2/+; Rab27aFrt/Frt)." (PMID 38383468, 2024).
cancer (continued). "In addition to cancers resistant to anti-PD-L1 therapy, cancer growth of MC38 mice, a colorectal cancer model which shows a partial response to anti-PD-L1 therapy, is also suppressed by Rab27A knockout." (PMID 38726017, 2024).
infection (19 papers, 2008 to 2025). The state of being infected such as from the introduction of a foreign agent such as serum, vaccine, antigenic substance or organism. "Moreover, in contrast to wild-type C57BL/6 mice, we detected no statistical difference in IFN-γ production by splenocytes following ex-vivo stimulation with HspX or Mtb whole cell lysate when we used Rab27a-deficient mice for the 10 day infection." (PMID 28262829, 2017). "We further investigated whether the impact of Rab27a expression is associated with infection MOI." (PMID 41217171, 2025). "Specifically, we show that Rab27a associates with OROV glycoproteins and, along with Myosin Va, is found in viral-induced compartments at late infection stages." (PMID 39213446, 2024). "There is an increasing colocalization of Rab27a with structures containing OROV proteins as the infection progresses." (PMID 39213446, 2024). "All inflammatory cytokines showed higher levels in the cardiac tissue of WT mice than in Rab27a-KO mice in the early stages of infection (within 7 days)." (PMID 36634130, 2023). "Then, we found that both HL-1 cells and HeLa cells exhibited highly efficient infection when treated with WTexo-CVB3 or Rab27a-KOexo-CVB3 for 12 h, as determined by western blotting with a specific anti-VP1 antibody." (PMID 36634130, 2023). "The NAb titers in CVB3-infected Rab27a-KO mice were higher than those in infected WT mice from 7 days to 42 days post-infection." (PMID 36634130, 2023). "Overall, these data demonstrate that A. phagocytophilum exploits the Rab27a-dependent MVB exosome release pathway to disseminate infection by positioning its vacuole at and fusing with the plasma membrane to release DC organisms to the extracellular milieu." (PMID 36409075, 2022). "Exosomes were purified from serum of Rab27a-deficient and wild-type C57BL/6 infected mice and PBS-treated mice at days 10 and 20 post-infection." (PMID 28262829, 2017). "Similar effects of decreased viral RNA and protein protein abundances during Rab27a depletion were observed when cells were infected at a 1000-fold higher multiplicity of infection with HCV." (PMID 26305877, 2015). "Taken together, these data point to a significant role for Rab27a in the infection of oligodendrocytic cells with HSV-1." (PMID 23164453, 2012). "In these cells YFP-Rab27a located throughout the cytoplasm while HCMV-infection relocated YFP-Rab27a to the assembly site, as observed for endogenous Rab27a immunoreactivity." (PMID 21170347, 2010). "Interestingly, colocalization between OROV and Rab27a at the cell periphery is more prominent at the late stages of infection (24 h.p.i.)." (PMID 39213446, 2024). "However, the recipient splenic T and B cells, monocytes and NIH 3T3 cells, which lack virus receptors, showed inefficient infection after treatment with Rab27a-KOexo-CVB3 compared to that after infection with WTexo-CVB3." (PMID 36634130, 2023). "Infection of CMV increased the level of Rab27a, which was related to CMV production." (PMID 31068945, 2019). "Rab27a-deficient and wild-type C57BL/6 mice were infected with 106Mtb or M. bovis BCG by retro-orbital injection and the mice were sacrificed at different times post-infection." (PMID 28262829, 2017). "This was due to an elevated concentration of exosomes released upon infection of wild-type macrophages while no significant increase was observed for infected Rab27a-deficient macrophages." (PMID 28262829, 2017). "In addition, functional analysis confirmed a significant decrease of GFP-expressing cells 24 hour after infection of Rab27a-silenced cells with a GFP-tagged HSV-1." (PMID 23164453, 2012). "Finally, functional studies showed that Rab27a depletion produced a significant decrease on the infection rate." (PMID 23164453, 2012).
infection (continued). "The Golgi/early endosome associated adaptor protein AP1γ1 or the extracellular vesicle (EV) marker CD9 were absent in those viral fractions, suggesting that the presence of Rab27a is not due to contamination with cytosolic material or increased general release of EVs caused by infection." (PMID 39213446, 2024). "Similar to Rab27a, the immunofluorescence staining of MyoVa revealed a partial colocalization with OROV proteins, and this colocalization increased as the infection progressed." (PMID 39213446, 2024). "We show that Rab27a interacts with OROV glycoproteins and colocalizes with OROV during late phases of the infection cycle." (PMID 39213446, 2024). "The immunofluorescence analysis shows evidence of increased colocalization between Rab27a and OROV proteins in an infection time dependent manner." (PMID 39213446, 2024). "In vivo, BLOC-1,2,3, AP-3, Rab27a, and Syt VII mutant mice sacrificed at 18 days post-infection exhibited only a moderate decrease in viral load in the bone marrow, spleen, and thymus when compared to wildtype mice." (PMID 18629000, 2008). "Although viral protein expression was unaffected, indicating that virus entry occurs, Rab27b and Rab27a co-depletion led to a 73.09% (± 8.82%) reduction in the release of infections OROV particles, an effect that was stronger compared to the individual depletion of the Rab27 isoforms." (PMID 39213446, 2024). "Rab27a is still not widely studied in the infection context, with moderate to absent expression reported in uninfected urothelium from different species." (PMID 37939183, 2023). "Notably, RDV was accompanied by Rab5-, Rab27a-, or CD63-involved exosomes into the sieve tube cells of rice phloem after viruliferous leafhoppers feeding and then spread through rice phloem to establish initial infection." (PMID 34214032, 2021). "Although the trafficking and processing of Env were not affected in Rab27A-silenced cells, Rab27A ablation impaired HIV-1 cell-to-cell spread either through free viral particles or by trans-infection at the VSs." (PMID 34307340, 2021). "Analysis of the number of GFP-expressing cells 24 hours after infection with K26GFP virus, showed a significant decrease of these parameters in Rab27a-silenced cells compared to non-target control shRNA-expressing and non-transfected cells." (PMID 23164453, 2012). "Comparative analysis between GHSV-UL46 and K26GFP infection showed that, unlike capsid-tagged K26GFP virus, tegument-tagged GHSV-UL46 displayed partial colocalization with Rab27a (Manders coefficients: M1 = 0,72 M2 = 0,45)." (PMID 23164453, 2012).
neurodegenerative disease (2 papers, 2019 to 2021). A disorder of the central nervous system characterized by gradual and progressive loss of neural tissue and neurologic function. "The interaction of KIBRA with Rab27a in controlling exosome secretion may be involved in the initiation and progression of neurodegenerative diseases, although whether KIBRA confers a protective or destructive effect in neurodegenerative diseases remains unclear." (PMID 30967557, 2019).
bacterial infection (1 paper, 2019). "The LPS-induced decreased expression of Rab5, without similar effects on Rab27A, suggests that the regulatory interactions with the microtubule network may be slowed as a result of bacterial infection." (PMID 31547509, 2019).
RAB27A also shares sentences with these, for which no sentence is quoted: cervical cancer (5 papers); gastric cancer (4); inflammation (2); metastatic melanoma (2); mild cognitive impairment (2); acquired immunodeficiencies (1); acute kidney injury (1); acute myeloid leukemia (1); adenocarcinoma (1); allergic rhinitis (1); anaphylaxis (1); autoimmune disease (1); bile duct cancer (1); brain cancer (1); Cachexia (1); Charcot-Marie-Tooth disease type 2B (1); chorioretinal degeneration (1); chronic granulomatous disease (1); chronic kidney disease (1); chronic lymphocytic leukemia (1); cystic kidneys (1); dementia (1); endometrial cancer (1); Familial hemophagocytic lymphohistiocytosis (1); fibromatosis (1); genetic disease (1); Griscelli syndrome type 1 (1); head and neck cancer (1); hematological malignancies (1); Hypoinsulinemia (1).
A further 25 diseases each share a sentence with RAB27A in 1 paper.